GOLPH3 (golgi phosphoprotein 3)
Diseases named in the same sentence as GOLPH3 in open-access papers (continued):
Sharing a sentence is not in itself a finding about the gene and the disease.
cancer (continued). "The role of GOLPH3 in tumorigenesis may be related to its involvement in protein transport from the Golgi apparatus to the plasma membrane and increased glycosylation of cancer-associated glycoproteins." (PMID 33680216, 2021). "Although the role of GOLPH3 as a cancer driver in human solid cancers is well-established, the precise link between GOLPH3 and tumorigenesis is still unclear." (PMID 40136688, 2025). "An increasing number of studies has provided strong support for the notion that GOLPH3 overexpression is a cancer driver and can be used as a positive biomarker for tumor progression and poor prognosis." (PMID 40136688, 2025). "Golgi phosphoprotein 3 (GOLPH3), predominantly localized at the trans-Golgi network, has been implicated in the pathogenesis of various cancers." (PMID 39944595, 2025). "In the context of glycosylation, it has been proposed that GOLPH3 controls glycosphingolipid synthesis and plasma membrane composition, which, in turn, enhances Akt/mTORC1 signaling and promotes cancer cell growth." (PMID 40136688, 2025). "GOLPH3 is believed to promote cancer cell growth, inhibit cell death, and enhance migration through the regulation of signaling pathways like AKT/mTOR." (PMID 38828452, 2024). "GOLPH3 increases the glycosylation of cancer-relevant glycoproteins and regulates EGFR in glioblastoma cells via the modulation of its glycosylation and has a role in MDA-MB-231 cells, sustaining their bioenergetic function and their mitochondrial fission." (PMID 39329960, 2024). "Comparative analysis revealed elevated GOLPH3 protein levels in cancerous tissues versus normal tissues, with single-cell analysis indicating widespread GOLPH3 presence across various cell types in the cancer microenvironment." (PMID 38828452, 2024). "The higher the percentage of GOLPH3 positive cancer cells (“A” score in IRS scale) in the prostate and the higher the staining intensity (“B” score in IRS scale) in the metastatic lymph node, the efficacy of RP was lower (p<0.05)." (PMID 37790749, 2023). "Previous studies have found that Golgi phosphoprotein 3 (GOLPH3) is overexpressed in various cancers, including PCa." (PMID 37790749, 2023). "LVI was significantly less common in patients with a percentage of GOLPH3 positive cancer cells between 11-50% than 51-80% (0% vs. 75%; p=0.026) and >80% (0% vs. 83%; p=0.004)." (PMID 37790749, 2023). "GOLPH3 has been identified as an oncogenic protein in cancer localized to the Golgi, and in a previous study, we found that its interactions with PI4P and sialyltransferases (ST3Gal4 or ST6Gal1) are essential for the regulation of sialylation." (PMID 37451482, 2023). "GOLPH3 expression was also positively correlated with cancer stem cell marker CD44 expression as well as EMT markers associated with increased tumor invasion and metastasis." (PMID 37508488, 2023). "We also found a statistically significant relationship related to the efficacy of RP, similar to that already described, between the intensity of staining GOLPH3 positive cancer cells (“B” score in IRS scale) in metastatic lymph node (p=0.026)." (PMID 37790749, 2023). "GOLPH3—a highly conserved protein of the trans-Golgi network—has become a key player in cancer biology." (PMID 37508488, 2023). "The genome location of GOLPH3 (chr5p13) is frequently amplificated in many cancers; GOLPH3 protein modulates cell size, promotes growth-factor-induced mTOR signaling in human cancer cells, and changes the response to an mTOR inhibitor rapamycin in vivo." (PMID 36967990, 2023). "Another important function of GOLPH3 is its response to DNA damage, enhancing cell survival and proliferation, and finally promoting development of cancers (Buschman, Rahajeng & Field, 2015)." (PMID 36967990, 2023). "Chi-squared tests revealed a positive relationship between GOLPH3 levels and clinical-stage (P < 0.001), cancer death, T classification (P = 0.025), N classification (P < 0.001), and M classification (P = 0.009)." (PMID 35190555, 2022).
cancer (continued). "Our dissection of the molecular mechanisms underpinning GOLPH3 interactions with the mTOR pathway now sets the stage to understand the notable effects of GOLPH3 overexpression on mTOR signaling and autophagy observed in a broad set of cancer contexts." (PMID 36435842, 2022). "These PKD2-mediated actions cause GOLPH3-induced activation of the PI3K/AKT/mTOR signaling pathway, thus promoting cancer cell proliferation." (PMID 35805075, 2022). "One of the more relevant examples is Golgi phosphoprotein 3 (GOLPH3), whose functions in cancer progression and signaling pathways have been fully reviewed by Sechi and collaborators." (PMID 35805075, 2022). "The high expression of GOLPH3 not only enhances the proliferation and the invasion of cancer cells but also promotes radiochemotherapy resistance, thus leading to cancer progression and poor prognosis." (PMID 36358544, 2022). "Increased levels of GOLPH3 following copy number alteration results in increased levels of LCS in cancer cells, which in turn leads to increased GSL biosynthesis." (PMID 35159178, 2022). "The authors identify GOLPH3 as a master regulator of glycosphingolipid metabolism and show that in cancer, the increased GOLPH3 levels alter glycosphingolipid synthesis and plasma membrane composition, thus promoting mitogenic signaling and cell proliferation." (PMID 35805075, 2022). "The PKD2 pro-proliferative function is mediated by inducing the PI3K/AKT/mTOR signaling pathway via GOLPH3, an oncogene that stimulates cancer cell growth by regulating this signaling cascade." (PMID 35805075, 2022). "Golgi phosphoprotein 3 (GOLPH3) is an oncogene involved in the development of carcinoma in a number of organs and a candidate metastasis gene in human cancer.Different studies have investigated the role of GOLPH3 in PCa." (PMID 36387263, 2022). "In bladder cancer, GOLPH3 mediates gemcitabine and cisplatin chemoresistance by promoting cancer stem cell phenotypes." (PMID 35073936, 2022). "Using these cell lines and models, we confirmed that GOLPH3 promotes cancer cell invasion and migration, both in vitro and in vivo." (PMID 35190555, 2022). "GOLPH3 was identified as the first Golgi resident oncoprotein; since then, compelling evidence has shown that GOLPH3 accelerates cancer progression." (PMID 35190555, 2022). "A strong relationship between miRNAs and GOLPH3 in human cancers has been reported in the literature." (PMID 34497755, 2021). "Rab1A and GOLPH3 have been demonstrated to be oncogenes and are upregulated in a number of human cancers, including colorectal, prostate and gastric cancers." (PMID 34195689, 2021). "Analysis of a publicly available NSCLC dataset (NCBI/GEO/GSE75037) revealed that GOLPH3 mRNA levels were significantly higher in NSCLC cancer tissues compared with those in normal human lung tissues." (PMID 34671013, 2021). "Other GDTLs we detected like CXCR1, VASP, ZYX, GPR137 and GOLPH3 were reported as known markers in many cancers." (PMID 33179221, 2021). "Studies suggest that GOLPH3 is highly expressed in numerous cancers and related to proliferation, tumorigenicity, and drug resistance." (PMID 34671013, 2021). "Rab1A and B interact with Golgi phosphoprotein 3 (GOLPH3), a protein involved in post-Golgi transport that is considered a Golgi oncoprotein and associated with several types of cancer." (PMID 34769517, 2021). "In this study, we found that the GOLPH3-transduced cell exosomes treatment enhanced the cancer stem cell-like phenotype and cancer metastasis more effectively than treatment with recombinant WNT3A." (PMID 34671013, 2021). "Tumor cell in vitro experiments or experiments in nude mice have clarified the role of the GOLPH3 protein in cancer cell proliferation, metastasis, and angiogenesis." (PMID 33680216, 2021). "GOLPH3 overexpression has been correlated with poor prognosis in several cancers, but the molecular mechanisms that link GOLPH3 to malignant transformation are poorly understood." (PMID 34571985, 2021).
cancer (continued). "Previous studies have demonstrated the proliferative and anti-apoptotic effects of GOLPH3 as well as its role in efficient Golgi-to-PM trafficking in cancer." (PMID 34671013, 2021). "Thus, the study of genes associated with cancer in birds could provide clues about the genetic bases associated with this difference and suggest additional model systems that could help to understand the biology of the GOLPH3 gene family." (PMID 34127736, 2021). "GOLPH3 can promote the proliferation and inhibit the apoptosis of cancer cells via activation of the Wnt signaling pathway and can enhance the expression of β-catenin." (PMID 34807928, 2021). "For example, transfection of miRNA-3135b in HCT-15 cancer cells sensitised the cells to DNA damage by downregulating the expression of GOLPH3, resulting in reduced levels of mTORC1 signalling." (PMID 34195689, 2021). "A particularly interesting example of an oncogenic trafficking protein is Golgi phosphoprotein 3 (GOLPH3), which is highly expressed in several cancers." (PMID 32433026, 2020). "Remarkably, in different types of cancer, increasing levels of GOLPH3 are correlated with poor survival, being proposed as a biomarker of malignant progression." (PMID 33238647, 2020). "According to the results of double staining immunohistochemistry, there was high SOX8 and GOLPH3 expression in tumor tissues from TSCC patients relative to adjacent non‐cancer counterparts." (PMID 32307911, 2020). "Accumulating evidence shows that oncoprotein GOLPH3 participates in the development of a variety of cancer types." (PMID 33134174, 2020). "Recent reports indicate that GOLPH3 overexpression can be used as a positive biomarker for tumor progression and poor survival in these cancer types." (PMID 32023813, 2020). "GOLPH3 has been proved to be the oncoprotein, which participates in the development of a variety of cancer types." (PMID 32307911, 2020). "Our findings also highlight the need of considering possible functional heterogeneity in the effects of overexpressed GOLPH3 in different cancer cell lines." (PMID 33238647, 2020). "Over‐expression of GOLPH3 is believed to enhance the proliferation and growth of cancer cells, which is achieved by activating the nuclear factor kappa B (NF‐B), Wnt, and mTOR signal transduction pathways." (PMID 32307911, 2020). "According to immunoblotting analysis, SOX8 and GOLPH3 protein expression was dramatically up‐regulated within TSCC tissues compared with that in matched para‐cancer counterparts." (PMID 32307911, 2020). "Since this discovery, GOLPH3 has been postulated as the first oncoprotein of the Golgi apparatus, being identified overexpressed in an increasing number of different types of cancer." (PMID 32790781, 2020). "Here we summarize current knowledge on the oncogenic pathways involving GOLPH3 in human cancer, GOLPH3 influence on tumor metabolism and surrounding stroma, and its possible role in tumor metastasis formation." (PMID 32023813, 2020). "Experimental data in cancer cell lines or in nude mice revealed the role of GOLPH3 in cell proliferation, metastasis formation and angiogenesis." (PMID 32023813, 2020). "GOLPH3 is also considered the first oncoprotein of the Golgi apparatus, with important roles in several types of cancer." (PMID 32790781, 2020). "Data from Listanti and collaborators identified the requirement for GOLPH3 for controlling cancer metabolism." (PMID 32023813, 2020). "Nonetheless, it remains largely unclear about the mechanism of the elevated GOLPH3 expression in cancer cells." (PMID 32307911, 2020). "Further studies addressing the functional role of GOLPH3 binding to RAB1A and RAB1B will provide insights on GOLPH3 function in normal and pathological conditions such as in cancer." (PMID 32790781, 2020). "During the last ten years, increasing experimental evidence positions GOLPH3 as an important player in cancer biology." (PMID 32790781, 2020).
cancer (continued). "Further studies showed that GOLPH3 promotes the development of cancer by activating mammalian target of rapamycin (mTOR) signaling, enhancing AKT activity, and decreasing forkhead box O1 (FOXO1) transcriptional activity." (PMID 31737112, 2019). "Cancer stemness is also maintained by other factors, such as Golgi phosphoprotein 3 (GOLPH3), yin and yang 1 (YY1), and neurofilament light (NEFL)." (PMID 31861937, 2019). "Golgi phosphoprotein 3 (GOLPH3) has been reported to be involved in the development, and in the DNA damage response, of various human cancers." (PMID 31557970, 2019). "The over-expression of GOLPH3 confers survival benefit to cancer cells, suggesting that Golgi fragmentation is necessary for cell survival." (PMID 31557970, 2019). "The expression of GOLPH3 in cancer and adjacent normal tissues from NSCLC patients was detected by immunohistochemistry (IHC) staining, which included assignment of staining intensity and area of positive staining using the semi-quantitative scoring system." (PMID 31737112, 2019). "Over-expression of GOLPH3, by the way, is reported to promote proliferation and tumorigenicity in many other kinds of human cancer." (PMID 31557970, 2019). "Golgi phosphoprotein 3 (GOLPH3) is a protein of the trans-Golgi membrane and plays a certain role in cancer cell survival, differentiation and proliferation." (PMID 31205749, 2019). "The immunostaining of FAP-a in stromal fibroblasts and GOLPH3 in carcinoma cells was scored semiquantitatively as 3 (high), 2 (low), and 1 (absent of staining) based on the staining intensity, respectively." (PMID 31921678, 2019). "A better understanding of the activity and mechanism of GOLPH3 will contribute to explore cancer pathogenesis, and provide novel targets and therapeutic strategies for patients with HCC." (PMID 29914442, 2018). "It has been elucidated that GOLPH3 can regulate cell size, enhance growth-factor-induced mTOR signaling in many human cancer cell lines like A549 and CRL-5889, and alter the response to rapamycin which is a mTOR inhibitor in vivo." (PMID 29914442, 2018). "Similar results have been reported in several types of cancers 12, 14, 15, which demonstrates the vital role of the oncogene GOLPH3 in tumorigenesis and metastasis." (PMID 28332316, 2017). "A recent study established that GOLPH3 has oncogenic properties mediated via mTOR signaling, and that GOLPH3 gene at 5p13 region is frequently amplified in a number of cancers." (PMID 27706081, 2016). "We performed immunohistochemical analysis for GOLPH2 and GOLPH3 and evaluated their expression in three compartments: cancer cells, TAMs and CAFs." (PMID 27706081, 2016). "In the context of cancer pathogenesis, GOLPH3 was shown to enhance signaling through the mammalian target of rapamycin (mTOR)." (PMID 25691054, 2015). "It was shown that Golph3 enlarges cell size, enhances growth-factor-induced mTOR signaling in human cancer cells, and increases the sensitivity to an mTOR inhibitor." (PMID 26156018, 2015). "Golgi phosphoprotein 3 (GOLPH3) has been reported to be involved in the development of several human cancers." (PMID 26375441, 2015). "Given the strong connection between GOLPH3 expression and cancer survival, a comprehensive knowledge of the molecular circuits requiring this protein will be essential to identify novel cancer therapeutic strategies." (PMID 25691054, 2015). "Knockdown of GOLPH3 inhibited the proliferation, migration and invasion of cancer cells, and tumor growth in a xenograft mouse model." (PMID 26375441, 2015). "A minute dissection of the molecular pathways that require GOLPH3 protein will be helpful to develop new therapeutic cancer strategies." (PMID 25691054, 2015). "Mechanistically, GOLPH3 regulates cell size, enhances growth-factor-induced mTOR signalling in human cancer cells, and alters the response to rapamycin in vivo." (PMID 26196085, 2015).
cancer (continued). "Since the first demonstration of GOLPH3 oncogenicity, a large number of studies supported the correlation between GOLPH3 up-regulation and poor survival in many cancers, despite the anticancer chemotherapy used in oncology." (PMID 25691054, 2015). "For further confirming the oncogenic role of GOLPH3 in human cancer univariate and multivariate analyses were used and our results revealed that overexpression of GOLPH3 in PDAC was correlated with pTNM stage, lymph node metastases and liver metastases." (PMID 25104140, 2014). "Recent clinical studies have indicated that high levels of GOLPH3 expression promote tumorigenesis and progression of several types of malignancies, and correlates with poor survival in various cancers." (PMID 24444035, 2014). "Those investigations have uncovered some potential links of GOLPH3 with cellular function to tumorigenesis which is very important for us to further understand how this protein contritute to cancer pathology." (PMID 25104140, 2014). "GOLPH3, which encodes a peripheral membrane protein of the Golgi stack and may have a regulatory role in Golgi trafficking, was recently shown to enhance growth-factor-induced mTOR signaling and consequently alter response to rapamycin, an mTOR inhibitor, in cancer cells." (PMID 23433318, 2013). "An increasing number of studies have found GOLPH3 upregulation in several types of cancers, thus indicating a role for GOLPH3 as a positive regulator of cancer progression." (PMID 22905766, 2012). "At 5p13 GOLPH3 was recently established as a new oncogene that was gained in lung and other cancers." (PMID 21151896, 2010). "In this review, we summarize the recent progress in dissecting the cellular and molecular functions of GOLPH3 that may lead to new therapeutic interventions for cancer." (PMID 40136688, 2025). "However, gene silencing coupled with the cDNA overexpression of both genes pinpointed GOLPH3 alone as the gene targeted for activation in cancers with 5p13 amplification." (PMID 40136688, 2025). "In contrast, GOLPH3 knockdown reduces tumorigenicity in various types of cancer cell lines." (PMID 38391929, 2024). "Furthermore, our exploration into GOLPH3’s involvement in critical oncogenic pathways, such as the G2M checkpoint, strengthens the possibility of its impact on cancer progression." (PMID 38828452, 2024). "It would therefore be of interest to investigate whether the SYS1-ARFRP1-ARL5-ARMH3-PI4KB axis contributes to both viral replication and GOLPH3-driven tumorigenesis, potentially offering additional targets for anti-viral and anti-cancer interventions." (PMID 39580461, 2024). "GOLPH3, a recently discovered molecule, has emerged as a player in cancer progression." (PMID 38828452, 2024). "To investigate the functional role of this upregulation, we examined whether BPA could promote cancer progression via GOLPH3 upregulation." (PMID 38828452, 2024). "The most upregulated GO terms emphasized the importance of synaptic components and assembly, suggesting a role for GOLPH3 in cellular communication and neuronal-like signaling in cancer, given BPA exerts well-established endocrine-disrupting effects on similar pathways." (PMID 38828452, 2024). "Furthermore, a recent study reported that GOLPH3 promotes angiogenesis and cancer cell proliferation by activating NF-κB signaling pathway." (PMID 37479687, 2023). "In addition, a statistically significant correlation was found between the percentage of GOLPH3 positive cancer cells in metastatic lymph nodes and the occurrence of lymphovascular invasion (LVI) (p=0.02)." (PMID 37790749, 2023). "Furthermore, GOLPH3’s tentacles extend into cancer progression by exerting regulatory control over a slew of signaling pathways, notably the PI3K-AKT-mTOR axis." (PMID 37762375, 2023).